DLEC1 (DLEC1 cilia and flagella associated protein)
Diseases named in the same sentence as DLEC1 in open-access papers (continued):
Sharing a sentence is not in itself a finding about the gene and the disease.
chronic obstructive pulmonary disease (1 paper, 2019). A chronic and progressive lung disorder characterized by the loss of elasticity of the bronchial tree and the air sacs, destruction of the air sacs wall, thickening of the bronchial wall, and mucous accumulation in the bronchial tree. "By applying metaFARVAT to data from a family-based study and a case-control study, we identified a few promising candidate genes, including DLEC1, which is associated with chronic obstructive pulmonary disease." (PMID 31275357, 2019).
cutaneous melanoma (1 paper, 2013). A primary melanoma arising from atypical melanocytes in the skin. "The potential role of mutated DLEC1 in nevogenesis and melanoma pathogenesis makes DLEC1 a candidate tumor suppressor gene in cutaneous melanoma." (PMID 24222856, 2013). "Three different missense mutations were found in other genome or exome sequencing studies, making DLEC1 a candidate tumor suppressor gene in cutaneous melanoma, probably acting by inhibition of cell proliferation." (PMID 24222856, 2013).
familial cancer (1 paper, 2015). "We are not aware of earlier reports of DLEC1 germline mutations associating with familial cancer, illustrating the research value of WGS in the clinic." (PMID 26023681, 2015).
gastric adenocarcinoma (1 paper, 2015). "Compared with a former study documenting that DLEC1 methylation was detected in 33.8% of gastric adenocarcinoma serum samples by methylation-specific PCR, our result (80.5%) was much higher." (PMID 26550574, 2015).
gastric tumours (1 paper, 2009). "We found that DLEC1 underwent promoter methylation-associated silencing in most CRC and gastric tumour cell lines and primary tumours, in a tumour-specific manner." (PMID 19156137, 2009). "The methylation status of DLEC1 was further examined in primary CRC and gastric tumour samples using the well-validated MSP analysis." (PMID 19156137, 2009). "We demonstrated that DLEC1 was absent in most colorectal and gastric cell lines due to promoter methylation, and methylated in a significant part of primary CRC and gastric tumours in a tumour-specific manner." (PMID 19156137, 2009).
Hodgkins lymphoma (1 paper, 2012). A heterogeneous group of malignant lymphoid neoplasms of B-cell origin characterized histologically by the presence of Hodgkin and Reed-Sternberg (HRS) cells in the vast majority of cases. "We first examined the expression of DLEC1 mRNA in 25 non-Hodgkin and Hodgkin lymphoma cell lines by RT-PCR." (PMID 23050586, 2012). "Furthermore, DLEC1 was specifically methylated in the sera of 3/13 (23%) Hodgkin lymphoma patients." (PMID 23050586, 2012).
Infertility (1 paper, 2020). "Therefore, the lack of Dlec1 is probably responsible for infertility in olt/olt male mice, though careful investigation for the involvement of Ctdspl and Vill is necessary." (PMID 33144677, 2020).
leiomyoma (1 paper, 2012). A well-circumscribed benign smooth muscle neoplasm characterized by the presence of spindle cells with cigar-shaped nuclei, interlacing fascicles, and a whorled pattern. "Incubation of primary leiomyoma smooth muscle cells with a DNA methyltransferase inhibitor restored KLF11, DLEC1 and KRT19 mRNA levels." (PMID 22428009, 2012). "To understand the in vivo relevance of how DNA methylation affects gene function, we analyzed protein levels of KLF11, DLEC1 and KRT19 in human leiomyoma and matched normal myometrial tissues using western blot." (PMID 22428009, 2012). "5-aza-dC treatment of primary cultured leiomyoma smooth muscle cells led to an increase in KLF11 mRNA by 1.4-fold, DLEC1 mRNA by 2-fold, and KRT19 mRNA by 2.4-fold suggesting that these three genes are epigenetically regulated in leiomyomas." (PMID 22428009, 2012).
lymph node metastasis (1 paper, 2014). "We had found that DLEC1 methylation was significantly higher in patients with recurrence, as compared with that in patients without recurrence among patients without lymph node metastasis." (PMID 25574068, 2014). "In addition, DLEC1 methylation did not correlate with tumor size (P = 0.243), depth of invasion (P = 0.066), lymphatic invasion (P = 0.102), venous invasion (P = 0.074), TNM staging (P = 0.063), Lauren classification (P = 0.050), and lymph node metastasis (P = 0.089)." (PMID 25574068, 2014).
melanocytic nevus (1 paper, 2013). A neoplasm composed of melanocytes that usually appears as a dark spot on the skin. "Since the pathogenic role of DLEC1 D215N mutation was not completely elucidated until now, it is not clear if this point mutation contributes with an increased susceptibility for melanoma or for melanocytic nevus development." (PMID 24222856, 2013).
melanoma (1 paper, 2013). A malignant, usually aggressive tumor composed of atypical, neoplastic melanocytes. "Primary melanomas (n = 81) paired with synchronous or asynchronous metastases (n = 21) from 81 melanoma patients and melanocytic nevi (n = 28) were screened for DLEC1 D215N mutation." (PMID 24222856, 2013). "D215N somatic mutation in DLEC1 occurs with a relatively low prevalence in melanocytic nevi and primary melanomas." (PMID 24222856, 2013). "DLEC1 D215N somatic mutation (COSM36702) was identified in a melanoma cell line through whole genome sequencing." (PMID 24222856, 2013). "The aim of this study was to confirm the occurrence and estimate the prevalence of DLEC1 D215N mutation in formalin fixed and paraffin embedded tissue samples from melanoma and melanocytic nevi." (PMID 24222856, 2013). "Up to our knowledge, this is the first study on prevalence of DLEC1 D215N mutation in melanoma patients and in melanocytic nevi tissue samples." (PMID 24222856, 2013). "Nevertheless, the prevalence of DLEC1 mutations among primary melanomas, melanoma metastases, or benign melanocytic nevi remains undetermined." (PMID 24222856, 2013). "Therefore, a total of 81 primary melanomas paired with 21 metastases and 28 benign melanocytic nevi samples were successfully genotyped for DLEC1 D215 somatic mutation." (PMID 24222856, 2013). "DLEC1 D215N mutation (COSM36702) is a G > A substitution in codon 641 (ENST00000308059) which was identified in whole genome sequencing of a tumor cell line derived from melanoma metastases." (PMID 24222856, 2013). "DLEC1 D215N genotyping call rates were 91.9% (102 out of 111) in melanoma samples and 82.4% (28 out of 34) in melanocytic nevi samples (P = 0,119)." (PMID 24222856, 2013).
nevus (1 paper, 2013). Nevus (or naevus, plural nevi or naevi, from nævus, Latin for "birthmark") is the medical term for sharply circumscribed[1] and chronic lesions of the skin or mucosa. "DLEC1 D215N heterozygous somatic mutation was also found in two cases (7.1%) of acquired melanocytic nevi: a dermal nevus of the face and a compound nevus in the trunk without atypical features." (PMID 24222856, 2013).
prostate carcinoma (1 paper, 2017). A carcinoma that arises from epithelial cells of the prostate gland. "DLEC1 methylation was associated with higher PSA levels, higher Gleason score, and more advanced tumor stage, which could be a non-invasive epigenetic biomarker for prostate cancer." (PMID 28423531, 2017).
renal carcinoma (1 paper, 2009). A carcinoma arising from the epithelium of the renal parenchyma or the renal pelvis. "DLEC1 was first identified as a potential TSG involved in lung, oesophageal and renal cancers, but with no methylation detected." (PMID 19156137, 2009).
uterine tumors (1 paper, 2020). "DLEC1 expression could be restored with demethylating agents when downregulated, as demonstrated in lung, prostate, oral, nasopharyngeal, renal, ovarian, adrenocortical, and uterine tumors." (PMID 33153431, 2020).
tumor (21 papers, 2008 to 2026). "Abnormalities in DLEC1 methylation are potential diagnostic and prognostic epigenetic tumor markers." (PMID 33153431, 2020). "DLEC1 methylation was cancer-specific, as it was only rarely detected in matching normal lung tissue, and was strongly associated with stage II tumours and the spread of cancer to regional lymph nodes (P<0.0001)." (PMID 18594535, 2008). "DLEC1 methylation was positively associated with tumor size only (p = 0.04)." (PMID 26550574, 2015). "Thus, DLEC1 methylation can be associated with tumor growth." (PMID 26550574, 2015). "This study utilized public datasets and tumor samples to examine the expression and promoter hypermethylation of DLEC1 in normal and tumor tissues, to evaluate its potential as prognostic and immunotherapy marker." (PMID 42002658, 2026). "DLEC1, a well-recognized tumor suppressor and biomarker, undergoes promoter hypermethylation under PM2.5 exposure, resulting in transcriptional silencing that favors cell cycle progression and reduced apoptosis." (PMID 41345682, 2025). "The study found that expression levels of DLEC1 were significantly different between tumor and normal tissues (p = 0.0001)." (PMID 35936745, 2022). "DLEC1 is located at 3p22-p21.3 in humans, which is frequently missing in various tumours, indicating that this chromosome region is more unstable compared to other regions." (PMID 33144677, 2020). "Introduction of the DLEC1 expression vector into cancer cells or treatment with 5-aza-2′-deoxycytidine, which induces DNA demethylation, inhibits cell proliferation and/or malignancy, so DLEC1 is believed to act as a tumour suppressor." (PMID 33144677, 2020). "DLEC1 exhibits its cancer-inhibiting potentials by decreasing the invasiveness and metastasis of tumor cells and also by enhancing apoptosis and arresting the G1 phase of the cell cycle." (PMID 33153431, 2020). "The DLEC1 gene encodes the deleted in lung and esophageal cancer 1 protein (DLECI) that has tumor suppressive activities." (PMID 28459043, 2017). "A loss of function of DLEC1 was previously related with several cancers, suggesting that DLEC1 acts as a tumor suppressor gene." (PMID 24222856, 2013). "Among them, 10 genes have been reported in HCC, and ZMYND10, SYK, DAB2IP, and DLEC1 have been reported to be tumor-suppressor genes in HCC." (PMID 21625442, 2011). "The function of DLEC1 was further explored by examining the inhibitory effect of DLEC1 expression on tumour cell growth." (PMID 19156137, 2009). "Introduction of DLEC1 to silenced tumour cell lines HCT116 and MKN45 strongly suppressed their growth in colony formation assays." (PMID 19156137, 2009). "Reintroduction of DLEC1 into silenced tumour cells significantly suppressed tumour cell clonogenicity." (PMID 19156137, 2009). "Among the methylated target genes we identified, one is DLEC1 (Deleted in lung and oesophageal cancer 1), located at 3p22.3 – a common tumour suppressor locus with frequent genetic abnormalities in multiple cancers." (PMID 19156137, 2009). "As for DLEC1, MLH1 methylation was associated with stage II tumours and spread to regional lymph nodes." (PMID 18594535, 2008). "Although the function of DLEC1 is unclear, it suppresses tumour growth or reduces invasiveness of cancer cells." (PMID 18594535, 2008). "Functional analyses strongly suggest that DLEC1 is a tumor suppressor gene." (PMID 25574068, 2014). "We thus investigated the tumour suppressor function of DLEC1 by colony formation assay." (PMID 19156137, 2009). "Thus, DLEC1 is a functional tumour suppressor, being frequently silenced by epigenetic mechanism in gastrointestinal tumours." (PMID 19156137, 2009). "Differences in the tumor type may explain the variety in the serum methylation frequency of DLEC1." (PMID 26550574, 2015).
tumor (continued). "We also showed that the methylation-mediated silencing of DLEC1 could be reversed by genetic or pharmacologic demethylation, and restoration of DLEC1 suppressed tumour cell clonogenicity, providing significant evidence that DLEC1 functions as a tumour suppressor in these tumours." (PMID 19156137, 2009). "As there is no antibody available for DLEC1, we could not determine what proportion of methylated tumours would show loss or reduced DLEC1 protein expression." (PMID 18594535, 2008). "PM2.5 can drive hypermethylation of tumor-suppressive and repair genes such as RAD51, SOX2, and DLEC1, and hypomethylation of proto-oncogenic or stress-response genes including AHRR, OGG1, and NAT10." (PMID 41345682, 2025). "Downregulated tumour suppressors DIRAS3, DLEC1 and PEG3 (all, P < 0.001) were frequently observed in the immune group." (PMID 33522069, 2021). "We verified the effects of promoter DNA methylation on transcriptional inhibition of three tumor suppressor genes namely, KLF11, DLEC1, and KRT19." (PMID 22428009, 2012). "We selected three genes, the known tumor suppressors KLF11, DLEC1, and KRT19 and verified promoter hypermethylation, mRNA repression and protein expression using bisulfite sequencing, real-time PCR and western blot." (PMID 22428009, 2012). "From this set, we then selected three of the hypermethylated genes, Kruppel-like transcription factor 11 (KLF11), deleted in lung and esophageal cancer 1 (DLEC1), keratin 19 (KRT19) for further analysis based on their known tumor suppressor functions." (PMID 22428009, 2012). "DLEC1 was methylated in 38.7%, MLH1 in 35.7%, RARβ in 51.7%, RASSF1A in 32.4% and BLU in 35.3% of tumours." (PMID 18594535, 2008). "Interestingly, FAP81/DLEC1 protein could also play non-ciliary functions, as it was identified as a tumor suppressor." (PMID 33809498, 2021).
cancer (17 papers, 2008 to 2026). A tumor composed of atypical neoplastic, often pleomorphic cells that invade other tissues. "Decreased DLEC1 expression is found in various cancers; hypermethylation of the DLEC1 promotor region causes this decreased expression." (PMID 33144677, 2020). "Hypermethylation of the DLEC1 promoter is associated with its transcriptional repression in a wide variety of malignant tumors originating from lung, esophagus, kidney, ovary, nasopharynx, and liver." (PMID 22428009, 2012). "Cancer patients with high DLEC1 expression showed improved overall and progression-free survival under immune checkpoint inhibitor therapies, such as anti-CTLA4, anti-PD1 and anti-PDL1." (PMID 42002658, 2026). "DLEC1 promoter hypermethylation is a promising biomarker for cancer prognosis and potential immunotherapy response prediction." (PMID 42002658, 2026). "High DLEC1 expression correlated with better prognosis in several cancer types and with increased immune cell infiltration." (PMID 42002658, 2026). "Deleted in lung and esophageal cancer 1 (DLEC1) is a tumour suppressor gene that is downregulated in various cancers in humans; however, the physiological and molecular functions of DLEC1 are still unclear." (PMID 33144677, 2020). "HMCan successfully detected H3K27me3 marks on the DLEC1 gene, which is commonly deleted in various carcinomas, as well as on the homeobox D (HOXD) gene cluster located at 2q31-2q37 chromosome regions." (PMID 24021381, 2013). "DLEC1 is localized in the cytoplasm ubiquitously expressed in all human tissues, and repressed in several human cancers." (PMID 22428009, 2012). "Silencing of RASSF1A, BLU, as well as DLEC1 by promoter CpG methylation had been extensively identified in multiple human cancers." (PMID 23050586, 2012). "In conclusion, we have established a cell system to investigate the effects of epigenetic modifications on expression of target genes, in particular DLEC1, which is silenced in human cancers including HCC." (PMID 24281182, 2010). "DLEC1 was frequently downregulated and methylated across multiple cancers." (PMID 42002658, 2026). "Deleted in lung and esophageal cancer 1 (DLEC1), a tumor suppressor gene, could reduce transcriptional activity and promote hypermethylation in several types of cancer, including CRC." (PMID 36120367, 2022). "This reversible nature of DLEC1 suggests that it could be a potential treatment target for these cancers." (PMID 33153431, 2020). "Whether the DLEC1 methylation status is correlated with the prognosis of cancer patients requires further retrospective studies." (PMID 26550574, 2015). "DLEC1 has been suggested as a tumor suppressor gene in several cancers." (PMID 24222856, 2013).
gastrointestinal tumours (1 paper, 2009). "The expression of DLEC1 and its regulation in digestive tumours have yet to be evaluated." (PMID 19156137, 2009).
DLEC1 also shares sentences with these, for which no sentence is quoted: adenoma (1 paper); chronic atrophic gastritis (1); esophageal cancer (1); follicular lymphoma (1); hepatocellular carcinoma (1); leukoplakia (1); peripheral T cell lymphomas (1); premature ovarian failure (1); reproductive system diseases (1); sarcoma (1); small cell lung carcinoma (1); T-cell lymphoma (1); teratozoospermia (1); Uterine leiomyoma (1).